IL10 (interleukin 10)
Diseases named in the same sentence as IL10 in open-access papers (continued):
Sharing a sentence is not in itself a finding about the gene and the disease.
breast cancer (continued). "It was shown that, compared with healthy controls, in the saliva of breast cancer patients, there is an increase in the content of both pro-inflammatory (IL-2, IL-6, and IL-18) and anti-inflammatory cytokines (IL-4 and IL-10)." (PMID 36286034, 2022). "There were also a large number of values below the LOQ for IL-10 and TNF-α and a significant heterogeneity by menopausal status was observed when we assessed the associations between TNF-α and breast cancer risk among women with quantifiable levels of TNF-α." (PMID 35430795, 2022). "Another subset of Tfh, termed T follicular regulatory cells, induces the differentiation of IL-10-producing B cells in breast cancer." (PMID 35350071, 2022). "Even though IL-10 is considered an anti-inflammatory cytokine, a dual role of IL-10 in breast cancer development was reported." (PMID 35331230, 2022). "After the injection of UA-liposomes in a murine breast cancer model, they reached the tumor tissue and reduced IL-10 and IL-6 secretion as well as Foxp3+ phenotypic Tregs cells by inhibiting STAT5 phosphorylation." (PMID 35335881, 2022). "Genetic depletion of either NRP2 isoform in macrophages resulted in a dramatic reduction of LPS-induced IL-10 production, defects in phagosomal processing of apoptotic breast cancer cells, and increase in cancer cell migration following co-culture." (PMID 35651620, 2022). "IL-10 is an immunosuppressive cytokine with an important role in the TME and high levels of serous IL-10 have been associated with poor survival in breast cancer patients." (PMID 35335881, 2022). "In breast cancer, IL-10 expression in tumors positively correlates with locally advanced disease, higher tumor grade, and hormone-receptor negativity." (PMID 35255925, 2022). "Against the background of breast cancer, the level of IL-10 increases, reaching a maximum at stage IIa and gradually decreasing at advanced stages of breast cancer." (PMID 36286034, 2022). "A recent clinical study demonstrated that KD therapy played a beneficial role by reducing TNF- α, and insulin, and increasing IL-10 in breast cancer patients." (PMID 36438725, 2022). "In this regard, we first studied IL10 expression using immunohistochemistry in breast cancer tissue microarrays containing 50 samples (40 breast cancer tissues, 10 normal breast tissues)." (PMID 33500726, 2021). "One study has shown that IL-10 produced by TAMs in a mouse model of breast cancer represses CD8+ T-cell response concurrent with the inhibition IL-12 from dendritic cells." (PMID 34207035, 2021). "Subsequently, IL-10 can inhibit tumor migration and progression, especially in the early stage of breast cancer." (PMID 34572719, 2021). "ELISA assay demonstrated that the levels of TNF-α and IL-10 in the medium of MDA-MB-231 cells co-cultured with U937 cells were higher than that in the medium of breast cancer cells alone." (PMID 33867819, 2021). "Increased MDSCs in TME up-regulated transforming growth factor-beta 1 (TGF-β1), vascular endothelial growth factor (VEGF), and Interleukin-10 (IL-10) in rodent breast cancer models." (PMID 34869378, 2021). "In summary, our findings indicate that CCL16 expression is up-regulated by IL10/STAT3 signaling in breast cancer in vitro and in vivo." (PMID 33500726, 2021). "In breast cancer, macrophage-derived IL-10 overexpression resulted in tumor development via inefficiency of CD8+ T cell-dependent responses to chemotherapy." (PMID 34717710, 2021). "Analysis of tumor tissue from 50 postpartum and 7 np breast cancer patients, grouped by reproductive categories.IHC of IL-10 and FoxP3." (PMID 33649008, 2021). "Of note, MDSCs become activated and expand upon operational stress during primary breast cancer resection and start to secrete TGFβ, VEGF and IL10 to promote lung metastasis in a 4T1 orthotopic breast cancer model." (PMID 34459003, 2021).
breast cancer (continued). "IL10 was, among others, identified as an exercise-induced muscle factor with a minor anti-proliferative effect on breast cancer cells." (PMID 34359731, 2021). "Delivering a synthetic microRNA mimic let-7b to activate TLR-7 and inhibit IL-10 production in breast cancer mouse model can effectively reprogram the function of TAMs/TIDCs, reverse the TME and inhibit tumor growth." (PMID 34625124, 2021). "It has been found that MDSCs produces IL-10 to decrease the production of IL-12 and promote self-polarization to M2 in spontaneous metastatic 4T1 mouse mammary carcinoma, which requires intercellular contact and can be partially reversed by gemcitabine." (PMID 34625124, 2021). "In breast cancer cells, down-regulation of miRNA-141 inhibits IL-10 and leads to up-regulation of COX-2, PGE-2, and TNF-α expression." (PMID 32582189, 2020). "Cox regression analysis further indicated a prognostic significance of MTDH and IL-10 expression, age, and stage on five-year overall survival period in breast cancer." (PMID 33003428, 2020). "Our results also suggest IL-10 is a key factor eliciting immunosuppressive STAT3 signaling in CD103+ cDC1s in breast cancer." (PMID 31947933, 2020). "More studies on the mechanism and functional significance of MTDH- and IL-10 mediated breast cancer progression are warranted." (PMID 33003428, 2020). "Specifically, IL10 is a pleiotropic anti-inflammatory cytokine with a dual role in breast cancer, exhibiting both pro- and anti-tumor activities." (PMID 32300557, 2020). "Meanwhile, the protein expressions of MTDH and IL-10 were positively correlated in our breast cancer cohort (R = 0.442, p < 0.001, n = 265)." (PMID 33003428, 2020). "High IL-10 levels predict poor breast cancer prognosis and the IL-10 secreted by TAMs can inhibit T cell effector functions and induce regulatory functions that recruit Tregs." (PMID 33193690, 2020). "High levels of IL-10 have been reported to be responsible for drug resistance to breast cancer, in which the blockade of this cytokine resulted in diminished STAT3 activation and a decrease in Bcl-2 mRNA expression, and consequently the induction of apoptosis." (PMID 32244885, 2020). "Studies have shown that IL-10 plays an important role in the initiation and development of breast cancer." (PMID 32380517, 2020). "Specifically, in murine breast carcinoma, TAMs secrete increased levels of IL-10 upon paclitaxel or carboplatin chemotherapy." (PMID 33276524, 2020). "Previous research in breast cancer indicated that IL‐10 and IL‐6 inhibit DC maturation through repression of miR‐155 upregulation." (PMID 30628173, 2019). "In human breast cancer patients, IL-8 and IL-10 expression levels are abnormally high and this has been associated with advanced clinical stage and poor prognosis." (PMID 30987001, 2019). "CXCL18 induces IL4, IL13, and IL10 in TAMs promoting initiation and invasion of breast carcinoma cells via NF-κB and AP-1 pathways." (PMID 31398937, 2019). "M2 TAMs produce IL-10 at the tumor site leading to resistance of breast cancer to paclitaxel treatment and this resistance can be abrogated with the administration of an IL-10 neutralizing antibody." (PMID 30356656, 2018). "TLR2 agonists fed to neu transgenic mice significantly inhibits breast cancer growth and leads to inhibition of immune responses by production of IL-10 and regulatory T-cells." (PMID 30517191, 2018). "To this end, we investigated COX-2, PGE2 and IL-10 signals to elucidate the action mechanisms of açaí in the breast cancer inflammatory process." (PMID 29609579, 2018). "A separate, elegant study confirmed the role of IL-10 in progression of mammary tumors in the setting of post-lactational involution." (PMID 30187085, 2018). "Cisplatin-treated rats exhibited significantly increased levels of TNF-α (p < 0.001), IL-6 (p < 0.01), and IL-8 (p < 0.001) whereas, significantly decreased the level of IL-10 (p < 0.01) on the 5th day when compared with breast cancer control rats." (PMID 28420987, 2017).
breast cancer (continued). "The addition of Compound C to metformin-treated breast cancer cells significantly increased the expressions of IL-4, IL-10 and IL-13 when compared to metformin treatment alone." (PMID 28157701, 2017). "It is noted that two well‐characterized cytokines, TGF‐β1 and IL‐10, have been reported to be secreted by Tregs and also contribute to tumor promotion in breast cancer." (PMID 28993429, 2017). "Consistent with the RNA expression, protein secretion from the metformin-treated breast cancer cells also showed decreased expressions of IL-4, IL-10 and IL-13 in the medium and an increased expression of IFN-γ." (PMID 28157701, 2017). "As shown inour previous experiments, breast derived ASCs,especially breast cancer ASCs, express IL-10 andTGF-β1." (PMID 28367424, 2017). "Mechanistically, CUR pre-treatment ameliorated the cisplatin-induced nephrotoxicity by inhibiting the pro-inflammatory cytokines like TNF-α, IL-6, IL-8, and augmenting anti-inflammatory cytokine (IL-10) in mammary tumor bearing rats." (PMID 28420987, 2017). "In breast carcinoma, increasing infiltration of pDCs is related to high levels of IL-3, IL-6, IL-10, IL-15, IP-10, monocyte chemotactic protein-1, and RANTES." (PMID 29085361, 2017). "In the breast cancer tissue sections studied, there was in situ expression of IL-10 and TGF-β and therefore the likely presence of induced FOXP3+ Tregs." (PMID 27777963, 2016). "Regarding anti-inflammatory interleukins, our study sustains a protector action of the anti-inflammatory cytokines IL-4 and IL-10 in female dogs' mammary tumors." (PMID 26989335, 2016). "The literature on survival differences among breast cancer patients with different IL10 haplotypes is extremely poor." (PMID 26112140, 2015). "Primary TAMs isolated from breast cancer tissue produced a large amount of IL-10 and arginase-1, and a small amount of IL-12/23, and exhibited a cluster of differentiation (CD)163high/CD206high phenotype." (PMID 26359357, 2015). "It is important to mention that IL-10 concentration is also decreased upon ectopic expression of miR-17 and miR-20a in breast cancer cell lines." (PMID 25884400, 2015). "It was proven by several authors that IL-10 levels in blood samples of breast cancer patients correlate directly with the clinical stage of the disease." (PMID 26112140, 2015). "Recent studies have demonstrated that increased IL-10 in the breast cancer microenvironment leads to therapeutic resistance through multiple potential mechanisms." (PMID 26106384, 2015). "IL-10 induction was also observed in a mouse model of implanted TSA breast cancer, where topical imiquimod was shown to synergize with radiation and low-dose cyclophosphamide in inhibiting tumor growth." (PMID 24624132, 2014). "In summary, ILT4 was found to be highly expressed in primary human ductal and lobular breast cancer cells, and its expression was significantly correlated with more IL-10 expression, less TILs amount and further lymph node metastasis." (PMID 24762057, 2014). "For post-menopausal women, significant associations with breast cancer risk were observed for NFKB1 ins/del and del/del genotypes, IL-8 TT genotype, IL-10 TT genotype, TNF c.-418 GA and AA genotypes, and TNF c.-488 GA genotype." (PMID 25559835, 2014). "A more recent study on the effect of combined use of paravertebral block and propofol, in breast cancer patients undergoing surgery, showed a reduction of protumorigenic cytokines, IL-1 and IL-8, and an increase of IL-10, an antitumor cytokine." (PMID 24683330, 2014). "For pre-menopausal women, significant associations with breast cancer risk were observed for NFKB1 ins/del and del/del genotypes, NFKBIA CT genotype, IL-8 TT genotype, IL-10 TT genotype, and TNF c.-418 GA and AA genotypes." (PMID 25559835, 2014).
breast cancer (continued). "LPS triggered increased expression of TLR4 downstream signaling pathway protein myeloid differentiation factor 88(MyD88) and resulted in interleukin (IL)-6 and IL-10 higher production by human breast cancer cells." (PMID 25299052, 2014). "IL-10 overexpression in breast cancer confers tumor growth and aggressiveness, and is considered as a prognostic indicator for breast cancer." (PMID 24762057, 2014). "The aim of this study was to determine the expression of cyclooxygenase 2 (COX-2), transforming growth factor-beta (TGF- beta), interleukin-10 (IL-10) and their prognostic significance in breast cancers." (PMID 22353218, 2012). "In this study, we evaluated the prognostic significance of the immunomodulatory signalling molecules COX-2, TGF-β, IL-10 and Ki67 in tumor epithelium and stromal areas of human breast cancer." (PMID 22353218, 2012). "There are few studies comparing COX-2, TGF-β, and IL-10 expression in mammary tumor cell areas and tumor stromal areas." (PMID 22353218, 2012). "Another example is breast cancer, which besides decreased T cell stimulatory ability, exhibits decreased IL-12 and increased IL-10 production." (PMID 20214814, 2010). "Breast cancer is another example with decreased T cell stimulatory ability, which also exhibit decreased IL-12 production and increased IL-10 production." (PMID 20976171, 2010). "Increased serum levels of the cytokines IL-6, IL-8 and IL-10 have also been observed in patients suffering from breast cancer as compared with healthy women." (PMID 17261184, 2007). "IL10 is over expressed in breast tumours and exogenous administration can mediate regression of tumour growth and breast cancer metastases in mice models." (PMID 16842617, 2006). "The cytokines of the IL-1 family, IL-4 and its receptor, IL-6 and IL-10 are important candidate genes as they play an important role in breast cancer pathogenesis." (PMID 16842617, 2006). "Mononuclear cells from breast cancer patients exhibit increased IL10 production and IL10 serum levels correlate with stage of the disease." (PMID 16842617, 2006). "In a separate study IL10 expression was detected in 40 of 52 breast cancer specimens examined using immunohistochemical methods." (PMID 11870535, 2002). "Since IL-10 can limit the severity of severe cutaneous reactions by inhibiting inflammation in kitw/w-v mice, it is pertinent to consider that this cytokine has a negative effect on malignant epithelial cell proliferation, such as that in breast cancer." (PMID 41596472, 2026). "As expected, it was demonstrated that IL-10 production was increased in breast cancer cells." (PMID 40584290, 2025). "However, there is currently insufficient evidence to support IL-10 as a potential preventive mediator against breast cancer; therefore, further research is required." (PMID 40584290, 2025). "In conclusion, IL-10 contributes to a tolerogenic tumor microenvironment in breast cancer." (PMID 41007766, 2025). "In breast cancer specifically, IL-10 levels tend to increase with higher tumor grade and burden." (PMID 41007766, 2025). "In breast cancer patients, IL-10 levels are often elevated in both tumor tissue and circulation." (PMID 41007766, 2025). "IL-10 is another cytokine released by TANs that contributes to immune evasion in breast cancer." (PMID 40486614, 2025). "In addition, the Jagged1-Notch pathway was triggered in aromatase inhibitor-resistant breast cancer cells, resulting in macrophage differentiation toward M2 TAMs and increased production of IL-10." (PMID 40584290, 2025). "Furthermore, we found that CD8+ cells in breast cancer patients exhibited heightened levels of PD-L1 and reduced capacity to respond to IL-10." (PMID 39389979, 2024). "On the other hand, the role of IL-10 in breast cancer is still unclear." (PMID 38314029, 2024).
breast cancer (continued). "CD4+ T cells have two subsets—Th 1 and Th 2 cells—and some clinical data observed unbalanced Th 1/Th 2 levels in patients with breast cancer, where Th 2 cells released the cytokines IL-4 and IL-10 and suppressed the host immune system, exhibiting a tumour-promoting effect." (PMID 39624160, 2024). "Similarly, in ovarian cancer, bladder cancer, glioblastoma and breast cancer, IL-6 and IL-10 secreted by CSCs converted TAMs to M2 phenotype." (PMID 38613794, 2024). "Also, the expression of the cytokines IL-6, IL-8, and IL-10 in the breast cancer cells increased following exposure to P. acidilactici and its CFS for 24 and 72 h." (PMID 38314029, 2024). "Furthermore, researchers have discovered an increase in Bregs expressing CD19+, CD24+, and CD38+ and producing IL-10 in breast cancer patients." (PMID 39507526, 2024). "Also, it has been demonstrated that the IL-10 gene transcription and translation were impacted by the SNPs in the IL-10 promoter region, leading to aberrant cell division and emergence of breast cancer (Ref." (PMID 38186186, 2024). "It has been reported that IL-10 secreted by cancer cells is involved in reduction in cellular adhesion, and its expression by breast cancer cells may modulate a decrease in the adhesion potential of DBMSCs." (PMID 39768220, 2024). "Additionally, MEIS2‐mediated IL10 contributes to breast cancer cell growth, knockdown IL10 significantly reduced the proliferation rate of MEIS2‐KD breast cancer cells." (PMID 38711262, 2024). "Additionally, IL-10 antibody enhanced the efficacy of OK-432’s locoregional immunotherapy for mouse breast cancer ascites." (PMID 38279997, 2024). "The real‐time PCR analysis showed that the expression level of IL10 is highly upregulated in MEIS2 knockdown cancer cells, while significantly decreased in MEIS2 overexpressed cells, indicating that MEIS2 can affect the IL10 expression level in breast cancer cell." (PMID 38711262, 2024). "IL-10, which is responsible for controlling cellular immunity, may play a role in suppressing immunity in breast cancer, as well as creating an antitumor response." (PMID 39175950, 2024). "Nevertheless, the precise role of IL-10 in oncogenesis remains controversial, with reported anti- and pro-tumor effects observed in various malignancies such as thyroid cancer, non-small cell lung cancer, breast cancer, and colorectal cancer." (PMID 38279997, 2024). "For example, in breast cancer, tumor-infiltrating pDCs may contribute to immune tolerance by inducing regulatory T cells (Tregs) or producing immunosuppressive cytokines such as interleukin-10 (IL-10)." (PMID 38927922, 2024). "In addition, IL-10 can suppress T-cell proliferation and activity in breast cancer and inhibit T-cell-stimulated anti-tumor immunity by down-regulating MHC class II (APC)." (PMID 36835413, 2023). "Neither IL-10 1082 AA (OR = 0.708, 95% CI = 0.213–2.47) nor IL-10 1082 AG (OR = 0.930, 95% CI = 0.266–2.883) were associated with breast cancer." (PMID 37501757, 2023). "In animal model studies, induced expression of IL-10 in breast cancer cells reduces tumor growth." (PMID 36693957, 2023). "Furthermore, TAMs induce doxorubicin resistance in breast cancer by upregulating IL-10 via the IL-10/IL10-receptor/STAT3/Bcl-2 signaling pathway." (PMID 37369757, 2023). "Thus, low levels of IL-2 and IL-10 found in relapsed ER (+) breast cancer patients reflect a decreased ability to respond quickly to therapy." (PMID 37520880, 2023). "For example, Lactobacilli R389 fermented milk could delay breast cancer growth by reducing serum IL-6 and increasing IL-10 in breast and tumor-infiltrating immune cells." (PMID 37221044, 2023). "Thus, in many cancers such as breast cancer, cytokines including leptin, IL-1B, IL-6, IL-8, IL-23, IL-17, and IL-10 stimulate while others including IL-2, IL-12, and IFN-γ, inhibit cancer proliferation and/or invasion and enhance the body’s anti-tumor defense." (PMID 36835413, 2023).